STAT3 (signal transducer and activator of transcription 3)
Diseases named in the same sentence as STAT3 in open-access papers (continued):
Sharing a sentence is not in itself a finding about the gene and the disease.
breast cancer (continued). "In this study, we determined for the first time that inhibition of STAT3 activation relies on Ca+2 disbalance and ROS generation in PSD-A treated breast cancer cells." (PMID 33013353, 2020). "In this study, we observed overexpression and co-localization of IKKα and STAT3 in human breast cancer tissues as well as in H-Ras transformed human breast epithelial (H-Ras MCF-10A) and breast cancer (MDA-MB-231) cells." (PMID 33396715, 2020). "The functions of STAT1, STAT3, STAT5, and STAT6 in breast cancer formation, progression, prognosis and prediction have been documented." (PMID 32754201, 2020). "Gemini vitamin D analogue BXL0124 inhibits CD44-STAT3-mediated breast cancer invasion and metastasis by decreasing CD44 expression and STAT3 activation, as well as preventing CD44 binding to JAK2 and STAT3 in the cytoplasm." (PMID 33335857, 2020). "For example, Lnc-BM (a lncRNA related to breast cancer brain metastasis), binds to JAK2 and modulates its kinase activity through the Lnc-BM/JAK2/STAT3/ICAM1 pathway." (PMID 32083005, 2020). "Recently, suggestions have been made for using the anti-psychotic drug pimozide to inhibit STAT3 and STAT5 in breast cancer patients." (PMID 32164570, 2020). "Moreover, Faecalibacterium prausnitzii, the most well-known species in Faecalibacterium genus, could inhibit the secretion of interleukin-6 (IL-6) and the phosphorylation of Janus kinases 2 (JAK2)/signal transducers and activators of transcription 3 (STAT3) in breast cancer cells." (PMID 32272885, 2020). "G-CSF and GM-CSF from cancer cells activate the STAT3 and STAT5 pathways, which repress interferon regulatory factor-8, as reported in a previous mouse model of breast cancer." (PMID 32726950, 2020). "First, S1PR1 signaling in T cells enhances the tumor infiltration of Treg in a STAT3-dependent manner, reducing CD8 + TIL and increasing breast cancer and melanoma growth in mice." (PMID 31974367, 2020). "Recently, the interleukin-like epithelial-mesenchymal transition (EMT) inducer (ILEI) has emerged as a new cytokine that can activate STAT3 and drive both EMT and breast cancer stem cell formation through LIFR." (PMID 32023849, 2020). "NO released from MDSCs activates Notch and signal transducer and activator of transcription 3 (STAT3) in breast cancer cells, enhancing breast cancer stemness in co-cultures of human breast cancer cells and MDSCs." (PMID 32726950, 2020). "Our data demonstrate STAT3 and IL-10R inhibit the efficacy of a CD103+ cDC1 vaccine in murine breast cancer." (PMID 31947933, 2020). "Cancer cell-derived IL-6 activates the STAT3 pathway in MDSCs, subsequently upregulating indoleamine 2,3-dioxygenase in co-cultures of human CD33(+) myeloid progenitors with MDA-MB-231 breast cancer cells." (PMID 32726950, 2020). "AZD1480 treatment of cell lines and murine models, including but not limited to GBM, breast cancer, HNC, and ovarian cancer, inhibited STAT3 activation, cell viability, and tumor growth." (PMID 33521321, 2020). "In the current study the apoptosis-inducing and anti-proliferative effects of Naringenin together with cyclophosphamide were studied in breast cancer cells and the participation of JAK2/STAT3 pathway was investigated." (PMID 33680016, 2020). "Mechanistically, we elucidated that leptin/OBR further activated STAT3 to promote PAI-1 expression via miR-34a–dependent and miR-34a–independent mechanisms in breast cancer cells." (PMID 33371368, 2020). "For example, S1P promoted the activation of STAT3 in cardiomyocytes, and ABC294640 blocked NF-κB activity in multidrug-resistant breast cancer cells." (PMID 32670862, 2020). "Overexpression of COX2 by breast cancer cells was documented to trigger PGE2 secretion, subsequently upregulating STAT3-mediated transcription of IDO in fibroblasts." (PMID 33072086, 2020).
breast cancer (continued). "IL-11, secreted from the bone-specific metastatic breast cancer cell line (BoM-1833), promotes osteolytic bone metastasis by activating RANKL-independent osteoclastogenesis through the JAK1/STAT3 pathway." (PMID 32674405, 2020). "We also found that LNK can promote breast cancer cell to proliferate and migrate via activating JAK/STAT3 and ERK1/2 pathway." (PMID 32322171, 2020). "We next sought to natural compounds which can inhibit breast cancer cells via HIF‐1α and STAT3 pathways." (PMID 32065498, 2020). "Of note, phosphorylation of signal transducer and activator of transcription 3 (STAT3) can translocate into the nucleus to recruit on ZEB1 promoter, resulting in ZEB1 nuclear translocation in breast cancer cells." (PMID 33058500, 2020). "Homoharringtonine and IHT have been reported to inhibit transcription factor, signal transducer, and transcription 3 (Stat3) activation in gefitinib-resistant NSCLC and breast cancer cells, respectively." (PMID 33172112, 2020). "In breast cancer, HOXA1 transforms immortalized human breast epithelial cells stimulated by p44/42 MAPK pathway, signal transducer and activator of transcription 3 (STAT3) and STAT5B into an invasive malignant phenotype." (PMID 33763449, 2020). "In combination with the STAT3 studies above, this points to OSM activating multiple signaling pathways to promote breast cancer progression." (PMID 32023849, 2020). "We demonstrate that betavulgarin suppresses the proliferation of breast cancer and BCSC formation through the regulation of Stat3/Sox2 signaling in BCSCs." (PMID 32630026, 2020). "STAT3 inhibition and TLR7/8 pathway stimulation in MDSCs repolarize and suppress MDSCs from breast cancer patients." (PMID 33679700, 2020). "Exosomal miR-19a-3p suppresses breast cancer progression by inducing M1 macrophages polarization by regulating the expression levels of Fos-related antigen 1 (Fra-1), VEGF, and signal transducer and activator of transcription 3 (STAT3)." (PMID 32595638, 2020). "In line with the TCGA outcomes, up-regulated HNRNPA2B1 is concluded to promote breast cancer tumorigenic potential by activating extracellular-signal-regulated kinase 1/2 (ERK1/2), and signal transducer and activator of transcription 3 (STAT3)." (PMID 33362863, 2020). "Similar to breast cancer, STAT5 also has a dual role in HCC, where it can act as a tumour suppressor to counteract the tumorigenic effects of STAT3 signalling or as an oncogene in other circumstances." (PMID 32872372, 2020). "TAM-derived IL-10 display increased expression of bcl-2 and STAT3 genes, and the subsequent IL-10/STAT3/Bcl-2 signaling pathway induced TAM-mediated treatment resistance on co-culturing human breast cancer cell lines (T47D, BT549) and TAMs (THP-1)." (PMID 32726950, 2020). "Further, BCL6 was suggested as a drug target in combination with STAT3 in NSCLC cells, as well as in breast cancer cells." (PMID 32234966, 2020). "STAT3 and STAT5 expression can be found in all breast cancer subtypes and a down-regulation of both by different drugs was associated with reduced growth in breast cancer subtypes." (PMID 32699527, 2020). "Leptin-induced IL-8 activation via intracellular signaling molecules, such as STAT3, Akt, and ERK 1/2, facilitates EMT of breast cancer cells." (PMID 33123472, 2020). "In conclusion, we confirmed that that lncRNA-LOC645166 promotes STAT3 activation by recruiting NF-κB to the promoter region of GATA3, thus eliciting ADR tolerance in Breast cancer cells." (PMID 32461377, 2020). "NANOG contributes to carcinogenesis via activating and preserving CSCs properties by regulating some genes or pathways, such as Stat3/Snail EMT, in many carcinomas, including breast cancer." (PMID 33375053, 2020). "Overexpression of miR-124 reduced the activity of STAT3 signaling pathway and enhanced apoptosis upon irradiation in NSCLC and in HER2-positive breast cancer." (PMID 32585857, 2020).
breast cancer (continued). "In breast cancer, the source of IL-30 was stromal leukocytes, and IL-30 stimulated the proliferation of breast cancer cells in a gp130/IL-6R- and STAT1/STAT3-mediated mechanism." (PMID 32023849, 2020). "Further, several studies have demonstrated that STAT3 up-regulates MMP2, MMP7 and MMP9 in breast cancer cell lines, proteins that are heavily associated with EMT." (PMID 32391382, 2020). "Oncogenic pathways such as IL-6/Stat3, EGFR, NOTCH and TGF-β1 are involved in breast cancer (BC) cell mesenchymal phenotype and stemness." (PMID 32894152, 2020). "In breast cancer, abiraterone, targeting CYP17A1, was negatively correlated with STAT3 (r = −0.969) to the greatest extent compared with other compounds." (PMID 32486001, 2020). "In the current study, STAT3 was found to regulate the protein expression of IKKα, but not that of IKKβ or IKKγ, in H-Ras MCF-10A cells and MDA-MB-231 breast cancer cells." (PMID 33396715, 2020). "Mechanistically, we revealed that adipocyte-derived leptin activated STAT3 to directly enhance PAI-1 expression, or indirectly affect the PAI-1 level by repressing miR-34a, thereby promoting PAI-1-induced breast cancer metastasis." (PMID 33371368, 2020). "Leptin was found to stimulate OBR expression via STAT3/G9a/miR-200c signaling cascade, and OBR promoted the formation of breast cancer stem-like cells (CSC)." (PMID 33371368, 2020). "So, IL-6/JAK/STAT3 signaling is believed as a key signaling pathway for tumor progression, and has been confirmed in many types of solid tumors such as HCC, breast cancer and lung adenocarcinomas." (PMID 33153467, 2020). "The Si-STAT3 transfection reduced the proliferation and the invasion of linc00514-OVE breast cancer cells." (PMID 32943090, 2020). "It was reported that stem cell-like breast cancer cells showed high STAT3 activation and the JAK2/STAT3 signaling pathway is important in maintaining stem cell characteristics." (PMID 32326231, 2020). "The detail molecular mechanism of TA2 spontaneous breast cancer is very complex and more experiments are needed to confirm the relationship between FGFR2/STAT3 signaling pathway and the tumorigenesis in TA2 mice in the future." (PMID 32432040, 2020). "Meanwhile, enhanced IRE1 activity has been demonstrated to increase the production of protumorigenic cytokines in breast cancer cells to survive paclitaxel, and ATF6 is required to promote mTOR activation and STAT3 signaling to gain chemoresistance." (PMID 33396303, 2020). "Our data establish the importance of STAT3 signaling in CSC-mediated resistance to endocrine therapy and the potential of SFX-01 for improving clinical outcomes in ER+ breast cancer." (PMID 32472077, 2020). "In this review, we briefly discuss some pathways we believe important to breast cancer metastasis, including TGF-β, NF-κb, and STAT3." (PMID 32929060, 2020). "In human breast cancer cells (MDA-MB 231), STAT3 phosphorylation and telomerase activity were also decreased by auranofin, but N-acetyl-L-cysteine (a scavenger of ROS) pretreatment restored STAT3 and telomerase activity." (PMID 32695747, 2020). "Of note, STAT3 was activated through phosphorylation in H-Ras MCF-10A and MDA-MB-231 cells as well as human breast cancer tissues to a greater extent than their normal counterparts." (PMID 33396715, 2020). "STAT3 is important for ANO1 transcription in response to IL-6 in pancreatic acinar cells and in response to EGF in breast cancer cells." (PMID 33250781, 2020). "Triggering of the TLR2/MyD88 signaling pathway by TEV derived from thymoma, mammary carcinoma or colon carcinoma cells and containing HSP72, has been shown to induce IL-6 production by MDSC and autocrine activation of STAT3." (PMID 32878277, 2020). "SCARA5 plays an important role in tumourigenesis and metastasis of breast carcinoma by inhibiting ERK1/2, STAT3 and AKT pathways." (PMID 33247676, 2020).
breast cancer (continued). "Upon FIP200 depletion, they found a decrease in the phosphorylation of EGFR, with this resulting in decreased STAT3 activation and consequently in an impairment of ALDH+ breast cancer stem cells (BCSCs) tumorigenicity." (PMID 30728463, 2019). "Cucurbitacins B and D are reported to inhibit proliferation and induce apoptosis through STAT3 suppression in human NSCLC A549 cells and doxorubicin-resistant breast cancer MCF-7/ADR cells, respectively." (PMID 31719837, 2019). "In breast cancer cells, IL-6 dramatically induced the expression of TWIST1 and SNAIL1 via STAT3 activation, leading to the initiation of an EMT." (PMID 31123345, 2019). "We selected niclosamide based on available evidence of it potential to inhibit STAT3 phosphorylation and nuclear localization and systematically investigated its effects on adipocytes-induced EMT in MDA-MB-468 and MCF-7 breast cancer cells." (PMID 31383893, 2019). "This novel signature is significantly correlated with low survival in breast cancer and is enriched in basal-like patients, suggesting that co-activation of the WNT-PCP and STAT3 pathways drives tumor aggressiveness." (PMID 30654518, 2019). "STAT3 inhibition in TAM populations re-sensitizes breast cancer cells to paclitaxel, further suggesting tumor and TAM crosstalk is an essential component in STAT3-driven therapy resistance." (PMID 31684144, 2019). "MCF-7 and MDA-MB-231 human breast cancer cell lines and MCF-10A were overexpressioned or knockdown ERα-36 and STAT3 and tested for migration, invasion and proliferation assays." (PMID 31409371, 2019). "We next examined the effect of MTF on the activation of IL-6-induced STAT3 and NF-κB in MBCDF and MBCD17 primary breast cancer cells." (PMID 31337349, 2019). "Derived from the natural product classes of flavones and isoflavones, it was determined to decrease STAT3 Y705 phosphorylation and increase apoptosis in MDA-MB-231 breast cancer cells, as well as Erlotinib resistant non-small cell lung cancer (NSCLC) cells." (PMID 31671769, 2019). "However, IL-6-mediated STAT3 activation has frequently been suggested to be a protective mechanism in chemotherapy-induced cell death through the increased expression of anti-apoptotic proteins such as Bcl-2 or survivin in solid tumors such as breast cancer and prostate cancer." (PMID 30927911, 2019). "ERK1/2 together with STAT3 and AKT also promotes the functional proliferation and activity of MDSCs in breast cancer, where the three pathways are down-regulated by the onco-suppressor aminoacyl-tRNA synthetase-interacting multifunctional protein 1 (AIMP1)." (PMID 31117237, 2019). "In previous studies on breast cancer, activation of the JAK/STAT3 pathway was reported to increase the expression of ATX, which is suggested to represent a putative STAT3 target gene." (PMID 31455351, 2019). "Approximately 90% of the primary breast cancers overexpressed HER3, p-mTOR, p-4EBP1, p-JAK2, p-STAT3, and 50% overexpressed p-Paxillin." (PMID 31667338, 2019). "Aberrantly high levels of tyrosine-phosphorylated signal transducer and activator of transcription 3 (p-STAT3) are found constitutively in ~50% of human lung and breast cancers, acting as an oncogenic transcription factor." (PMID 31491838, 2019). "In all breast cancer cell lines tested, OSM specifically induced STAT3 phosphorylation (pSTAT3), while IL-1β induced phosphorylation of p65 (pp65), a subunit of the transcription factor NFκB." (PMID 31007849, 2019). "DNA damage activated miR-21 expression through recruitment of NF-κB and signal transducer and activator of transcription 3 (STAT3) to its promoter region and contributed to promoting cell invasion in breast cancer." (PMID 31514389, 2019). "Inhibitors and knock-down strategies showed that the JAK/STAT3 pathway regulates CPT1 and FAO, and thereby self-renewal in breast cancer CD44+/CD24− mammosphere TICs." (PMID 31661927, 2019).
breast cancer (continued). "By contrast, STAT3 was expressed at very low levels in luminal A (MCF-7 and T-47D) and HER2 (SK-BR-3 and MDA–MB-453) breast cancer cells." (PMID 31058868, 2019). "Regarding TIC-ness, it has been shown that conditioned medium from certain hypoxia-cultured breast cancer tissue and cell lines stimulated mammosphere formation via IL-6 and JAK2/STAT3-signaling." (PMID 31661927, 2019). "In breast cancer-initiating stem cells, when stimulated by VEGF, VEGFR2 binds to JAK2 and activates STAT3, and maintains cell self-renewal by promoting MYC and SOX2 expression and induces sphere formation." (PMID 30819137, 2019). "Stat3 phosphorylation activated Oncostatin M and the downstream S100A7 gene expression in breast cancer." (PMID 31731716, 2019). "Mechanistically, lnc-BM induced STAT3-dependent expression of CCL2 to attract macrophages to cancer cells, thus enhancing breast cancer brain metastasis." (PMID 31448238, 2019). "MTF efficiently decreases Vimentin, SNAIL and cell proliferation in mesenchymal breast cancer cells and also reverses IL-6-induced EMT by blocking STAT3 and NF-κB phosphorylation." (PMID 31337349, 2019). "In breast cancer, studies have begun to identify the mechanisms by which adipocyte-induced EMT occurs, among the identified pathways are the TGF-β/Smad axis, TGF-β/STAT3 axis and the IL-6/STAT3 axis." (PMID 31383893, 2019). "Inhibition of Stat3 activity subsequently results in attenuated activation of EMT transcription factors TWIST and SNAIL, inhibiting the induction of EMT in breast cancer cells." (PMID 31383893, 2019). "Treatment with GQ-ODN has demonstrated inhibition of STAT3 and tumor growth in in vivo models of head and neck squamous cell carcinoma (HNSCC), breast cancer, prostate cancer, and non-small cell lung cancer (NSCLC)." (PMID 31671769, 2019). "This study focused on the role of SIRT4 in the tamoxifen sensitivity of breast cancer and demonstrated that SIRT4 blocks the transcription and translation of MYC and CCND1 in ER‐positive breast cancer, through the STAT3 pathway." (PMID 31573734, 2019). "As PIM1 was significantly upregulated by IL-6/STAT3 activation, we further investigated the roles of PIM1 in IL-6-induced breast cancer cell EMT and stemness." (PMID 30989585, 2019). "Another possibility is that STAT3 interacts with other STATs in conjunction with ER, such as STAT5, which has some opposing effects against STAT3 signaling in breast cancer cells thus reducing the overall cancer cell aggressiveness." (PMID 31007849, 2019). "Leptin activates estrogen receptor (ER) signaling, as well as the JAK/STAT3 and PI3K/AKT signaling pathways, promoting the proliferation of breast cancer cells." (PMID 31500658, 2019). "In Trastuzumab-resistant HER2+ breast cancer, STAT3 feed-forward loops generate a TME rich with STAT3-activating cytokines that promote and maintain the mesenchymal/CSC phenotypes." (PMID 31684144, 2019). "HNK treatment also effectively inhibits stemness in breast cancer by concurrent activation of tumor suppressor LKB1 and suppression of oncogenic Stat3 signaling." (PMID 31618928, 2019). "We also proved that ERα-36 was also associated with STAT3 and influenced phospholyation and acetylation of STAT3, which was required for IL-6-induced MMP2 and MMP9 expression and breast cancer cell migration." (PMID 31409371, 2019). "In pleural malignant mesothelioma and breast cancer, ERK1/2 phosphorylates STAT3 on serine 727 and activates the transcriptional induction of indoleamine 2,3 dioxygenase (IDO), the enzymes producing kynurenine." (PMID 31117237, 2019). "(B, C) A combined panel of selected breast cancer and near-normal cell lines was reverse-transfected with 10 nM pooled JAK1, JAK2, STAT3 or KRAS siRNAs and cell viability determined after 6 days." (PMID 30777101, 2019). "Both STAT3 activation and ERK1/ERK2 signaling mediated by leptin have been described to act as a key event in ERα-dependent development of breast cancer." (PMID 31380268, 2019).